CGAS (cyclic GMP-AMP synthase)
Diseases named in the same sentence as CGAS in open-access papers (continued):
Sharing a sentence is not in itself a finding about the gene and the disease.
tumor (continued). "When the same local treatment outcome was obtained by EBRT and RNT, the distant anti-tumor effect of RNT was better than that of EBRT, which was related to the cGAS-STING pathway activation." (PMID 38831378, 2024). "On the other hand, RECQL4 overexpression reduces the recruitment of DCs and CD8+ T cells, reducing the “soil” on which cGAS‐STING and IFN‐I are produced, leading to tumor immune evasion." (PMID 38381090, 2024). "This complexity suggests that the impact of the cGAS-STING pathway extends beyond its immediate gene targets, influencing broader signaling networks within the tumor microenvironment." (PMID 38523155, 2024). "The anti-tumor potential of robust cGAS-STING pathway activation in GBM has been demonstrated by therapeutic use of the synthetic STING agonist cGAMP that promotes innate and adaptive anti-tumor immunity." (PMID 38389103, 2024). "Through the detection of proteins related to STING pathway in clinical tumor samples of CRC patients, we found that the levels of cGAS, STING, TBK1, IRF3 proteins and phosphorylation in CRC tissues all decreased." (PMID 39054486, 2024). "IFN-β, a downstream signal of the cGAS-STING signaling pathway, can also stimulate tumor cells to produce CCL2 and CCL7 and affect the recruitment of M-MDSC." (PMID 39464890, 2024). "A close association between the cyclic GMP‐AMP synthase‐stimulator of interferon genes (cGAS‐STING) pathway and tumor promotion exists, revealing prospective therapeutic targets." (PMID 38145335, 2024). "In this study, we summarize the activation pathway of the cGAS-STING pathway and its immunological function and elaborate on the key role of this pathway in immune escape mediated by the tumor immunosuppressive microenvironment." (PMID 39464890, 2024). "This pathway is regulated through various epigenetic mechanisms, with high methylation levels detected in the promoter region of cGAS and STING in many different types of tumor cells." (PMID 39606248, 2024). "Studies have shown that the cGAS-STING pathway can sense manganese ions (Mn2+) in the cytoplasm and promote antigen presentation of the tumor cells, improving the recognition and attack capabilities of the immune cells." (PMID 38724978, 2024). "cGAS/STING activation, in the context of cancer, occurs following detection of tumour derived micronuclei and nuclear double stranded DNA (dsDNA) fragments." (PMID 39403376, 2024). "For example, 7,12‐dimethylbenzene (a) anthracene (DMBA) is a carcinogen that activates the cGAS–STING signal and promotes skin tumorigenesis in mice by inducing DNA breaks." (PMID 38525112, 2024). "Here, we describe the cross-talk between cGAS in tumor cells and STING in endothelial cells, which enhances transendothelial migration of lymphocytes, vascular normalization, and anti-tumor immunity." (PMID 38177099, 2024). "PARPi therapy leads to the accumulation of cytoplasmic DNA, which activates the cGAS/STING pathway, thereby creating an influx of natural killer (NK) cells, T-lymphocytes, and tumor-infiltrating lymphocytes (TIL) within the TME." (PMID 38542143, 2024). "It has been shown that cGAS-STING pathway activates both innate and adaptive immune response, thereby facilitates the transformation of a "cold" tumor immune environment into a "hot" tumor-immune microenvironment." (PMID 38832958, 2024). "The importance of the cGAS-STING pathway and type I interferon (IFN) in anti-tumor immunity has been widely studied." (PMID 40012911, 2024). "Cytosolic dsDNA can activate the cyclic GMP-AMP synthase stimulator of the IFN gene signaling pathway, increase chemokine secretion, promote CAR-T cell infiltration, and enhance anti-tumor immunity." (PMID 39464890, 2024). "Uncovering immunological consequences of cGAS-STING activation during infections and in the tumor microenvironment has enabled new avenues for therapeutic interventions against cancer and infectious pathogens (13, –, 15)." (PMID 38095464, 2024).
tumor (continued). "Three factors that appear to be important include augmented cGAS/STING and type I IFN, as well as increased tumor infiltration of cytolytic CD8+ T cells in combination-treated tumors." (PMID 38912586, 2024). "This synergy involves activating the cGAS-STING immune response pathway, inducing immunogenic cell death, and elevating PD-L1 expression on tumor cells to reshape the inflammatory tumor microenvironment." (PMID 38566036, 2024). "Focusing specifically on DNA-sensing and nuclease-related genes, a multitude of genes, including RNASEH2A, RNASEH2B, and RNASEH2C, as well as cGAS, STING, TBK1, and IFNB1, were studied in tumor tissue of 53 patients with CRC compared to adjacent normal tissue." (PMID 39050748, 2024). "Intriguingly, the cGAS-STING pathway has been shown to play a crucial role in both the production of these inflammatory cytokines and the activation of immune cells’ anti-tumor response." (PMID 39445027, 2024). "The cGAS-STING pathway has emerged as a critical part of the innate immune defense of the host, and its role in tumor immunity has been elucidated." (PMID 39464890, 2024). "While enormous efforts have been made to understand the critical role of cGAS-STING in the immune system, details of its role in anti-tumor immunity are not fully understood, and further studies were warranted." (PMID 38921005, 2024). "The disruption of the BRCA1-PALB2 interaction was demonstrated to induce tumor immunosuppression and T lymphocyte infiltration in HCC through the cGAS-STING pathway." (PMID 38807595, 2024). "The precise mechanism responsible for the attenuation of the signaling pathway to IRF3 from cGAS/STING, despite the existence of cytoplasmic DNA in tumor cells, remains poorly understood." (PMID 38817608, 2024). "Recent studies indicate that cGAS-STING pathway activation can promote PD-L1 expression on cancer cells, potentially providing a means for these cells to elude the anti-tumor response." (PMID 39050748, 2024). "The involvement of cGAS-STING in DC activation and secretion of IFN-β has also been observed In HCC tumor models." (PMID 39334927, 2024). "As expected, we observed that the expression of cGAS was significantly lower in SW620 and LOVO tumor cells than in normal enterocytes NCM460." (PMID 38782895, 2024). "Oncogene-induced replication stress generates endogenous DNA damage that activates cGAS–STING-mediated signalling and tumour suppression." (PMID 38200309, 2024). "For instance, targeting replication stress with CHK1 inhibitor promoted cGAS-STING signaling and NKT cell immune responses, and led to tumor regression." (PMID 38167507, 2024). "The cGAS-STING pathway plays a crucial role in anti-tumoral responses by activating inflammation and reprogramming the tumour microenvironment." (PMID 38553448, 2024). "Inflammatory pathways, such as cGAS/STING, p38 mitogen‐activated protein kinase (p38‐MAPK), and JAK/STAT, play pivotal roles in carcinogenesis by modulating tumor immunity and the tumor immune microenvironment (TME)." (PMID 38988492, 2024). "Our experiments showed that mtDNA and nDNA release induced by the nanocomposites can greatly stimulate the cGAS‐STING pathway, induce stronger innate immunity, and achieve more significant tumor‐inhibition rates (up to 87%) than HC or HL treatment alone." (PMID 38193125, 2024). "This involves further activation of the cGAS-STING pathway and the generation of IFN-I, which promotes DCs antigen presentation and initiates CD8 + T cell-mediated tumor antigen-specific immune responses." (PMID 39285178, 2024). "The cytoplasmic DNA sensing cyclic GMP‐AMP synthase (cGAS) – stimulator of interferon genes (STING) pathway has been reported to link RT and tumor immunity to attack the “Achilles’ heel” of tumors." (PMID 38381090, 2024). "We next sought to directly link the tumor exosomal ENPP1 and cGAS‐STING signaling by introducing GW4869, an inhibitor of exosome synthesis and secretion, into a co‐culture system." (PMID 38498770, 2024).
tumor (continued). "To further explore the crosstalk of cGAS-STING between tumor cells and host cells, we first assessed cGAS and STING expression in tumor microenvironment." (PMID 38177099, 2024). "The cyclic GMP-AMP synthase (cGAS) - Stimulator of Interferon Genes (STING) pathway is a major line of defense against viral and bacterial infections and tumor onset." (PMID 38969014, 2024). "In summary, our data provided the first evidence of a relationship between tumor‐derived RECQL4 and cGAS/STING activation in radiation‐triggered DCs in HCC." (PMID 38381090, 2024). "Activating the cGAS/STING innate immune pathway is crucial and effective for anti-tumor immunotherapy." (PMID 40018367, 2024). "In turn, intratumoral infiltrating lymphocytes secrete IL-2 to activate tumor STAT5A signaling, which further synergizes with TET2 to epigenetically upregulate tumor cGAS, indicating a positive feedback loop." (PMID 38177099, 2024). "We first investigated the role of cancer cell-intrinsic cGAS and STING in tumor vascular normalization and anti-tumor immunity." (PMID 38177099, 2024). "For evaluating the role of PTEN expression on cGAS-STING activity and tumour immunogenicity, mRNA expression levels of interferon-stimulated genes, especially IFNB, IFIT2, IFI44, and IL6 were analysed." (PMID 38214828, 2024). "Recent research has strongly demonstrated the intricate involvement of the cGAS-STING signaling pathway in diverse cellular processes, including tumor cell senescence, autophagy, apoptosis, and the preservation of immune-related cell stemness." (PMID 39834588, 2024). "In TCGA database, tumor TET2, STAT5A, and cGAS expressions positively correlated with vascular normalization-associated genes including vascular stabilization, endothelial-lymphocyte interaction, pericytes and T cell chemotaxis." (PMID 38177099, 2024). "In summary, our findings elucidate a crosstalk between tumor and vascular endothelial cells in the tumor microenvironment via cGAS and STING essential for tumor vascular normalization and anti-tumor immunity." (PMID 38177099, 2024). "In genomically unstable cancers (i.e. cancers with a high degree of chromosomal instability), dsDNA released via exosomes can also activate cGAS/STING in immune and tumour cells." (PMID 39403376, 2024). "In irradiated tumor cells, the ZBP1-MLKL necroptotic cascade induces cytoplasmic accumulation of mitochondrial DNA (mtDNA), which activates the cGAS-STING pathway, thereby enhancing the type I IFN response." (PMID 38523155, 2024). "The activation of the cGAS-STING signaling pathway led to increased levels of type I interferons (IFNs) and tumor-infiltrating lymphocytes (TILs), consequently triggering an immunogenic reaction." (PMID 38240703, 2024). "Taken together, these data indicate that cGAS silencing and NF-κB p65 overactivation occurred simultaneously in SW620 and LOVO tumor cells." (PMID 38782895, 2024). "Activation of the cGAS-STING pathway has been proved to have significant potential in promoting anti-tumor immunity, especially in enhancing tumor efficacy against immune checkpoint inhibitors such as PD-1/PD-L1 antibodies." (PMID 39867908, 2024). "Overall, the relationship between pro- and antitumorigenic functions of the cGAS-STING pathway are complex and highly dependent on the genetic makeup of the tumor as well as the tumor microenvironment." (PMID 38660307, 2024). "Targeting the cGAS-STING pathway holds promise for overcoming immunosuppressive tumor microenvironments (TME) and promoting effective tumor elimination." (PMID 38185685, 2024). "In a word, Mn2+‐related nanomedicines can not only directly kill tumor cells by Fenton‐like reaction‐induced ROS, but also activate innate and adaptive immune responses by both ROS‐induced ICD and activation of cGAS‐STING pathway." (PMID 38063781, 2024).
tumor (continued). "The low expression of MYC in HNSCC induces DNA damage related cGAS-STING pathway, which increases the recruitment of chemokines by CD8 T cells, promotes tumor immune response, and inhibits the proliferation and migration of HNSCC." (PMID 39403369, 2024). "In the context of cancer therapy, targeting cGAS-STING signaling is a promising strategy to activate the innate immune system to fight and ultimately kill tumor cells." (PMID 38660307, 2024). "Both of these phenomena set in motion the cGAS-STING pathway, rendering tumours more amenable to RT and radioimmunotherapy." (PMID 38816831, 2024). "On the other side, host cGAS is dispensable but tumor cGAS is necessary for host STING-mediated vascular normalization and anti-tumor immunity." (PMID 38177099, 2024). "Conventional cancer therapies including radio- and chemotherapy can induce cGAS-STING and anti-tumor immunity alone or in combination with STING agonists and immune checkpoint blockade." (PMID 38660307, 2024). "The synergistic combination of NLRC3 inhibitors, cGAS-STING pathway agonists, and immune checkpoint inhibitors holds particular promise for enhancing anti-tumor immune responses on multiple fronts." (PMID 39439455, 2024). "The damaged dsDNA activates the cGAS-STING pathway to promote IFN-β expression, while IFN-β can upregulate tumor cell expression of PD-L1, increase CD3+ TILs and CD8+ TILs infiltration, and initiate adaptive immune responses." (PMID 38425343, 2024). "These complexities highlight the need for a nuanced understanding of the cGAS-STING pathway in cancer immunotherapy, considering factors such as tumor type, dose-dependent effects, and the dynamic nature of the TME." (PMID 39450170, 2024). "Mn‐N/C‐mediated catalytic reaction prompts the concurrent release of cytosolic DNA and Mn2+, which coordinately activate cGAS‐STING‐IFN signaling cascade, thereby robustly promoting CD8+T anti‐tumor immunity and suppressing tumor growth." (PMID 38308189, 2024). "Studies have shown that activation of the cGAS-STING pathway can induce type I interferon production, leading to CD8+ T cell activation and tumor regression in mouse dendritic cells." (PMID 39295867, 2024). "Above all, the combined system achieved the enhanced tumor synergistic immunotherapy through TME reprogramming via the peroxidase-like activity of the CoNCDs and cGAS–STING signaling pathway agonist synergistically." (PMID 37762239, 2023). "POLQ inhibition in HR-deficient PDAC also results in more cytosolic micronuclei, activating the cGAS-STING signaling pathway, enhancing transcription of inflammatory cytokines, and increasing immune infiltration in the tumor." (PMID 36976649, 2023). "Extensive studies have shown that Mn2+ can boost the activation of cGAS/STING to stimulate dendritic cell maturation and macrophage M1 polarization, ameliorate immunosuppression, and enhance the efficacy of tumor immunotherapy." (PMID 37575228, 2023). "cGAS-STING signaling regulates the crosstalk between tumor cells and immune cells in the tumor microenvironment (TME), emerging as an important DNA-damage mechanism." (PMID 37051596, 2023). "Over the past few decades, cGAS-STING as a center pathway of cytoplasmic DNA sensor induces a protective immune defense and provides anti-tumor immunity." (PMID 37051596, 2023). "Several immunotherapy approaches designed to initiate anti-tumor immune response were shown to activate the cGAS-STING pathway and the therapeutic effects of the treatments are correlated with the STING expression within the tumor microenvironment." (PMID 37889361, 2023). "SR717, a non-nucleotide small molecule STING agonist obtained by large-scale drug screening targeting the cGAS-STING pathway in THP1 cells, also showed notable anti-tumor activity in mouse tumor models." (PMID 37920470, 2023).
tumor (continued). "By hydrolysis of 2’,3’-cyclic GMP-AMP (cGAMP) in the extracellular space, ENPP1 reduces cGAS-STING signaling, further weakening anti-tumor immune response." (PMID 36761762, 2023). "Recently, several studies have shown that the cGAS-STING signaling is critical to protect against tumorigenesis and preserve the efficacy of anti-tumor therapies such as immune checkpoint therapy, chemotherapy and radiotherapy." (PMID 37781354, 2023). "cGAS and AIM2 are CDSs that are activated in the presence of cytosolic dsDNA and are expressed in various cell types, including immune and tumor cells." (PMID 37046775, 2023). "Nanozymes and cyclic GMP-AMP synthase (cGAS) the stimulator of interferon genes (STING) signaling pathway, as powerful organons, can remodel the tumor microenvironment (TME) to increase efficacy and overcome drug resistance in cancer immunotherapy." (PMID 37762239, 2023). "Here we revealed a critical role of PRMT1 in directly methylating cGAS and blocking cGAS/STING DNA sensing signaling, thus promoting tumor immune evasion, which provides a rationale for PRMT1 as a promising immunotherapeutic target." (PMID 37193698, 2023). "It was shown that DNA damage activated the cyclic GMP-AMP synthase-stimulator of interferon genes (cGAS-STING) pathway, resulting in increased tumor-infiltrating lymphocytes (TILs) and IFN-related gene expression." (PMID 37457685, 2023). "Given the role of the cGAS-STING pathway in activating immune surveillance, current studies have focused on innate immune function to exert anti-tumor effects." (PMID 37965570, 2023). "As an interesting observation, RFC1 was recently determined as a cGAMP importer in the cyclic GMP–AMP synthase (cGAS)–stimulator of interferon genes (STING) pathway that has a role in inflammation, cellular stress, and tumor angiogenesis." (PMID 37328777, 2023). "This review discussed the cGAS-STING signaling and its mechanism and biological function in traditional tumor therapy and immunotherapy." (PMID 37920470, 2023). "Collectively, these studies indicate that breast tumor cells can rewire the cGAS-STING signaling to promote cancer cell survival, tumor progression and metastasization." (PMID 38203626, 2023). "Consistent with this, simultaneous abrogation of MDA5 and cGAS, RIG-I and cGAS, or MAVS and STING impaired shPhf8-induced anti-tumor effects in vivo." (PMID 37454216, 2023). "The specific tumor stage, CIN state, genotype, and basal level of cGAS-STING activation will likely determine the therapeutic responses of the host to STING agonists or antagonists." (PMID 37122745, 2023). "cGAMP activated the cGAS-STING-IRF3 pathway, which modified the tumour immune milieu to reverse the Epithelial-Mesenchymal Transition (EMT) and PI3K/AKT pathways and prevent tumour metastasis." (PMID 37162544, 2023). "We also found that tumor significantly upregulated YAP/TAZ expression in TAMs, resulting in suppression of Type I IFN signaling in the context of cGAS-STING stimulation." (PMID 36757811, 2023). "Like NRF2, cGAS/STING signaling also has an ambiguous role in cancers, being able to promote tumor development and metastasis, as well as an immune-suppressive tumor microenvironment if persistently activated." (PMID 37189700, 2023). "Apoptosis mediated by the cGAS-STING pathway plays crucial roles in balancing innate immune responses, resisting infections, and limiting tumor growth." (PMID 36769349, 2023). "The cGAS-STING pathway is a type of DNA sensor, required for the spontaneous generation of tumor-specific immune responses in the tumor setting." (PMID 37771774, 2023). "The cGAS/STING signaling pathway, triggered by cytosolic DNA, has been reported as a critical activator of anti-tumor immune responses." (PMID 37833461, 2023). "Recently, several studies have reported that the cGAS-STING signaling is a prognostic biomarker in HCC, and can be acted as an adjuvant to enhance the anti-tumor efficacy." (PMID 37020586, 2023).